GAS6 (growth arrest specific 6)
Diseases named in the same sentence as GAS6 in open-access papers (continued):
Sharing a sentence is not in itself a finding about the gene and the disease.
tumor (continued). "The expression levels of AXL, GAS6, Claudin-1, and Cofilin-1 genes were investigated in a fresh, frozen tumor sample and normal adjacent tissue by real-time PCR (RT-PCR)." (PMID 31700829, 2019). "Tumor-infiltrating leukocytes were shown to provide the soluble ligand GAS6, which fueled tumor growth and metastatic outcome in several tumor models." (PMID 31775787, 2019). "In this study, the AXL and GAS6 gene expression differences between tumor stages were statistically significant." (PMID 31700829, 2019). "In the tumor microenvironment, Gas6 signaling can regulate a variety of pro-tumorigenic cellular functions and increased expression of Gas6 and MerTK predicts poor prognosis in many types of cancer." (PMID 31903163, 2019). "Together, these data indicate that Gas6 expression is induced in tumor models and negatively regulated by NF-κB activation in macrophages." (PMID 31903163, 2019). "The TAM receptors are a family of receptor tyrosine kinases with shared ligands Gas6 and Protein S that skew macrophage polarization towards a pro-tumor M2-like phenotype." (PMID 31088471, 2019). "In the background of fibrosis, sinusoidal endothelial cells, activated HSCs, and Axl-positive myofibroblasts as well as Kupffer cells release Gas6 into the tumor microenvironment of HCC, causing a Gas6-enriched HCC stroma." (PMID 31583026, 2019). "We have therefore now evaluated AXL and GAS6 levels in both tumor tissue and plasma as well as their relation to clinical course in EGFR‐mutated NSCLC patients before treatment with and after the development of resistance to EGFR‐TKIs." (PMID 31419057, 2019). "Inhibition of the Gas6-MerTK pathway in all these models reduced macrophages and neutrophils in the lungs of tumor-bearing mice." (PMID 31903163, 2019). "The Gas6/TAM pathway can exert multiple pro-tumorigenic effects both on tumor cells and stromal cells." (PMID 30700007, 2019). "The Gas6/Axl complex acts to promote tumor progression by altering the functions of cell migration, proliferation, and survival." (PMID 31110076, 2019). "In vivo, GAS6 overexpression shortened the overall survival of U266 orthotopic MM mice, while targeting of GAS6 by warfarin significantly increased survival and reduced tumor growth in this model." (PMID 31694201, 2019). "We then measured proliferation of these cell lines after treatment with Gas6 and found that Gas6 increased proliferation of all 3 cancer cell lines suggesting that the pro-tumor effects of Gas6-MerTK signaling are mediated via increased proliferation." (PMID 31903163, 2019). "The levels of AXL and of GAS6 mRNA in tumor tissue were evaluated by immunohistochemistry and chromogenic in situ hybridization, respectively." (PMID 31419057, 2019). "The invasive nature of tumour cells is the major prerequisite for cancer metastasis, and Gas6 is clearly involved in cancer invasion." (PMID 29386018, 2018). "Of relevance we demonstrated that hMENA regulate Axl expression in tumor cells and sustain the paracrine Gas6-Axl axis." (PMID 30400822, 2018). "For instance, tumours can instruct intratumoral macrophages to overexpress and secrete Gas6 by producing IL-10 and M-CSF in the microenvironment, and Gas6 binds to TAM receptors in tumour cells and immune cells, promoting tumour progression." (PMID 29386018, 2018). "The Axl ligand Gas6 is secreted by tumor cells, the vasculature, tumor-infiltrating leukocytes and bone marrow progenitor cells in the tumor microenvironment (TME)." (PMID 30567378, 2018). "As a result, high Axl receptor expression would lead to increased Gas6-independent signaling, promote tumor growth as well as EMT and metastasis." (PMID 30567378, 2018). "In this review, we described the Gas6 and TAM receptors and the involvement of Gas6/TAM in different cancers; we then discuss the roles of Gas6 in cancer cells, the tumour microenvironment and metastasis." (PMID 29386018, 2018).
tumor (continued). "Growth arrest specific 6 (Gas6) protein is expressed by both osteoblasts and fibroblasts within the bone, and mediates interactions with tumor cells within the endosteal niche." (PMID 29642534, 2018). "GAS6 regulates part of the conversion of tumor cells into stem cells via its receptor Mer that activates the mTOR signaling pathway following cell to cell contact." (PMID 30180883, 2018). "The Gas6/TAM axis affects the tumour microenvironment by modulating diverse cellular functions, including those of immune cells and VSMCs." (PMID 29386018, 2018). "Although tumor-associated macrophages are suggested to secrete Gas6 in the TME, the role of Gas6/Axl for the infiltration of macrophages remains an open issue." (PMID 30567378, 2018). "Intriguingly, the immunosuppressive effects of Gas6/TAM in tumour microenvironments also provide effective cancer treatment through the inhibition of Gas6/TAM." (PMID 29386018, 2018). "Tumours can induce intratumoral macrophages to overexpress and secrete Gas6 by producing interleukin-10 (IL-10) and macrophage colony-stimulating factor (M-CSF) in the microenvironment." (PMID 29386018, 2018). "The combination of AxL and growth arrest-specific gene 6 (Gas6) is responsible for tumor progression and migration." (PMID 30373180, 2018). "Axl/Gas6 signaling can induce apoptosis inhibition in a broad range of cells, and is involved in cell migration, essential for tumor invasiveness, metastasis and neoangiongenesis." (PMID 29876303, 2018). "In the context of cancer, TAM RTKs and particularly Gas6/Axl signaling contribute to survival of tumor cells in response to apoptotic stimuli." (PMID 30567378, 2018). "The interaction of Gas6/Axl with 14-3-3ζ activates JNK which subsequently switches TGF-β towards tumor-progressive functions by aberrant phosphorylation of the Smad3 linker region and increased transcription of pro-metastatic genes." (PMID 30567378, 2018). "Mertk-/- mice, and Mertkwt mice treated with warfarin to inhibit Gas6 experience increased tumor control following ionizing radiation in an adaptive-immune mediated manner in CT26 tumor models." (PMID 30400822, 2018). "Sources of Gas6 are considered to be cancer cells themselves and/or the tumor stromal microenvironment." (PMID 28878389, 2017). "Multiple studies have shown that GAS6 is secreted by diverse cell types, from the tumor and/or stromal cells." (PMID 28251492, 2017). "Several studies suggest that secretion of Gas6 from the tumor stromal microenvironment occurs in mice." (PMID 28878389, 2017). "To investigate the possible function of the stromal Gas6–tumor Axl axis, we stimulated NSCLC cells with Gas6 in vitro." (PMID 28878389, 2017). "Ultimately, we assessed the relationships among tumor Axl expression, stromal Gas6 and prognosis using clinical data." (PMID 28878389, 2017). "Among tumor infiltrating leukocytes TAMs produced the mitogen Gas6 accelerating primary tumor growth and metastasis." (PMID 28197019, 2017). "In the present study, we found a positive relationship between tumor Axl expression and stromal Gas6 expression and an increase in stromal Gas6 expression after chemotherapy." (PMID 28878389, 2017). "They reported that circulating leukocytes produce minimal Gas6 but once they have infiltrated into the tumor, they upregulate Gas6 expression, contributing to tumor growth." (PMID 28878389, 2017). "Independently of the AXL/GAS6 system, tumor cells develop a heterogeneous setup of resistance mechanisms to cancer drug treatments." (PMID 28675785, 2017). "The tumor-promoting properties of AXL can be stimulated by the TAM ligand GAS6, which binds to AXL with highest affinity if co-expressed within tumor cells." (PMID 28118606, 2017). "The positive relationship between tumor Axl expression and stromal Gas6 expression remains unexplained." (PMID 28878389, 2017).
tumor (continued). "Our results indicate that NSCLC and TNBC self‐sustaining tumor cells in 3D spheroids benefit from the activation of PDK‐RSK‐mTOR pathway in the context of high GAS6 secretion." (PMID 28675785, 2017). "Alternatively, GAS6 expressed by the tumor microenvironment was also shown to activate AXL in a paracrine manner." (PMID 28118606, 2017). "Five-year disease-free survival rates for patients with tumor Axl- and stromal Gas6-positive tumors (n = 37) was significantly worse than for the double negative group (n = 12) (21.9% vs 51.3%, p = 0.04)." (PMID 28878389, 2017). "As overexpression of AXL/GAS6 can contribute to tumor invasion, metastasis especially to the brain, and drug resistance against chemotherapy and targeted therapies in NSCLC, the AXL/GAS6 pathway can be promising therapeutic target for clinical inhibition." (PMID 28551766, 2017). "Secretion of GAS6 from the tumor microenvironment has been shown in colon, breast, and prostate cancers as well as in AML." (PMID 28251492, 2017). "Both tumor and stromal cells from the microenvironment can produce GAS6, fostering a crosstalk between the two cell populations." (PMID 28251492, 2017). "Based on these complex mechanisms, how do scientists design drugs that target Gas6/TAM to treat various tumours with the fewest side effects?" (PMID 28333143, 2017). "TAMs acquire, possibly by cancer-derived factors like IL-10, the capacity to produce high levels of Gas-6 that promotes tumour development." (PMID 28381274, 2017). "In a fraction of patients, Axl was found to be expressed in the tumor and Gas6 in both tumor and stroma." (PMID 28878389, 2017). "The results showed that AXL and GAS6 expressions are primarily localized both at the cytoplasmic membrane and within the cytoplasm of tumor cells, respectively." (PMID 28551766, 2017). "This axis can be both autocrine in nature (both TAMs/Gas6 co-expressed in tumor cells or in myeloid cells) or paracrine in nature (TAMs in tumor cells/Gas6 in myeloid cells) to augment TAM signaling in the tumor microenvironment." (PMID 27916840, 2016). "Stress conditions within the tumor microenvironment play an important role in the activation of GAS6/AXL signaling." (PMID 27834845, 2016). "The interaction of PS with the overexpressed TAMs via its ligands, Gas6 and Pros1, on the tumor cells induce several tumorigenic phenotypes including tumor cell survival, proliferation, chemoresistance as well as tumor metastasis." (PMID 27916840, 2016). "Genetic and pharmacologic inhibition of GAS6/AXL signaling in tumor models has begun to illuminate the diverse mechanisms by which this signaling pathway promotes tumor progression and drug resistance." (PMID 27834845, 2016). "Upon chemotherapy macrophages increase Gas6 synthesis, which significantly attenuates the cytotoxic effect of 5-FU chemotherapy on tumor cells." (PMID 27486820, 2016). "RTK-AXL/Gas6 signaling is in charge of regulating survival, proliferation, and migration in different types of cells in vitro, including tumor-derived epithelial, mesenchymal, and hematopoietic cell lines." (PMID 26848524, 2016). "These efforts are based on recent observations that in the tumor microenvironment, both over-expression of TAMs and its ligands (Gas6 or Pros1) occur concomitantly." (PMID 27916840, 2016). "Macrophage-derived Gas6 allegedly then serves to feed TAM-dependent pathways in the tumor cells, as an additional mechanism by which tumors alter the surrounding stroma for their own benefit." (PMID 27775650, 2016). "Clinically, GAS6 expression in tumor specimens has been shown to be an adverse prognostic factor in urothelial, ovarian, lung adenocarcinoma, gastric cancer, and glioblastoma." (PMID 27834845, 2016). "In cancer, GAS6/AXL signaling can be activated in an autocrine or paracrine manner with tumor cells as well as cells within the tumor microenvironment, including macrophages and endothelial cells producing biologically relevant sources of GAS6." (PMID 27834845, 2016).
tumor (continued). "Mechanistically, it was revealed that the tumor is able to instruct intratumoral macrophages to overexpress and secrete Gas6 by releasing Interleukin-10 (IL-10) and Macrophage colony-stimulating factor (M-CSF) into the microenvironment." (PMID 27775650, 2016). "High expression of GAS6 was detected in normal prostate tissues, while a decrease of GAS6 expression correlated with tumor aggressiveness." (PMID 27028863, 2016). "Research over the past decade has focused on elucidating the functional role of GAS6/AXL signaling within the tumor microenvironment as well as determining the molecular mechanisms by which GAS6/AXL signaling promotes tumor progression." (PMID 27834845, 2016). "To explore the role that GAS6 plays in tumor progression, we examined the extent to which GAS6 expression is correlated with PCa progression in men who underwent radical prostatectomy for localized prostate cancer." (PMID 27028863, 2016). "Together, these studies implicate GAS6/AXL signaling as an important pathway driving tumor growth, metastasis, and drug resistance." (PMID 27834845, 2016). "Gas6, expressed by tumor-infiltrating M2-like macrophages, enhances malignant properties of tumor cells including proliferation, invasion and colony formation." (PMID 27486820, 2016). "Combined IGF1R and AXL inhibitors are required to block the PSC-induced tumor cell phosphoproteome—suggesting a Boolean “OR” axis between PSC IGF1/GAS6 and PDA pAKT." (PMID 27087446, 2016). "In immunohistochemical stainings of human CRC samples, Gas6 was primarily expressed in tumor infiltrating immune cells." (PMID 27486820, 2016). "We first observed that high levels of endogenous GAS6 are expressed by disseminated tumor cells (DTCs) in the bone marrow, whereas relatively low levels of endogenous GAS6 are expressed in PCa tumors grown in a s.c. setting." (PMID 27028863, 2016). "With the generation of AXL deficient mice and the use of AXL inhibitors in immune competent tumor models, we will be able to better understand how GAS6/AXL signaling is utilized in tumor stromal crosstalk to promote tumor progression." (PMID 27834845, 2016). "While the discussion above has focused mainly on the up-regulation of TAMs and TAM ligands (Gas6/Pros1) in the tumor microenvironment, a final important factor, namely the concomitant dysregulation of PS in the tumor microenvironment also warrants mention." (PMID 27916840, 2016). "Future studies investigating the role of AXL signaling within individual stromal cell populations are needed to better understand the diverse roles of GAS6/AXL signaling within the tumor microenvironment." (PMID 27834845, 2016). "Genetic and therapeutic inhibition of GAS6/AXL signaling has been utilized to identify important functional roles for AXL signaling in tumor progression, metastasis, and drug resistance." (PMID 27834845, 2016). "We have recently shown that warfarin exerts its anti-cancer effects by inhibiting Gas6-mediated Axl activation in PDA tumor cells." (PMID 26438693, 2015). "Gas6, protein S and galectin-3, the ligands for Mer, have been also described to be frequently overexpressed in tumor tissues of NSCLC, suggesting that Mer receptor is continuously activated in NSCLC via autocrine and/or paracrine mechanisms." (PMID 25826078, 2015). "It is conceivable however that Gas6 overexpression in GBM can stimulate other TAMs in a paracrine manner or instead to supress an anti-tumour immune response." (PMID 25980499, 2015). "Our finding that GW9662 inhibition of PPAR-γ generates M2c-like macrophages and Gas6 release is in fact consistent with previously reported GW9662 suppression of anti-tumor immune responses." (PMID 25972766, 2015). "Next we assessed the levels of the AXL ligand GAS6 in tumor cell-conditioned media in order to determine the potential for autocrine activation of AXL in LPS oncogenicity." (PMID 26573603, 2015).
tumor (continued). "As M2c cells, TAMs also release Gas6, which facilitates tumor cell proliferation and probably immune tolerance to cancer." (PMID 25972766, 2015). "To locate the source of high serum Gas6, we compared the mRNA expression level of Gas6 in tumor and tumor-adjacent tissue from OSCC patients." (PMID 26207647, 2015). "We demonstrated that Gas6/Axl signalling converges on the integrin β3 pathway in the presence of the adaptor protein p130Cas, thus inducing tumor cell adhesion to the extracellular matrix and invasion." (PMID 26356564, 2015). "GAS6 showed a iuxtamembranous staining, 10% of cases displayed stromal positivity, indicating that the ligand can be provided by tumour microenvironment." (PMID 25966280, 2015). "The level of Gas6 mRNA in tumor tissue from OSCC patients was significantly increased when compared with tumor-adjacent tissue (P < 0.01)." (PMID 26207647, 2015). "Consistent with the mRNA level, comparison of Gas6 protein level between tumor tissue and tumor-adjacent tissue showed that the protein level of Gas6 in tumor tissue was also higher than in tumor-adjacent tissue." (PMID 26207647, 2015). "Our study demonstrated that serum Gas6 level was significantly increased in sera from OSCC patients and Gas6 expression was also increased in tumor tissues." (PMID 26207647, 2015). "One previous study reported that transcription factor Slug was a target molecule of the Gas6/Axl pathway in HCC cells, suggesting Slug is essential for the induction of tumor invasion by Gas6." (PMID 26207647, 2015). "Although the precise mechanism underlying this expression inconsistency has yet to be elucidated, it is postulated that while Gas6 mRNA is naturally of tumor origin, Gas6 protein as detected by IHC is generally exogenous." (PMID 23242819, 2013). "Within the cancer cohort, GAS6 expression is significantly higher in tumours from patients with residual disease (defined as those with observable lesions greater than 10 mm in size) than those without (P = 0.0156)." (PMID 23878800, 2013). "Statistically significant differences were found between the Axl IHC low and high groups with regard to age, gender, p-stage, and LN metastatic status, and between the Gas6 IHC low and high groups with respect to maximum tumor size and LN metastatic status." (PMID 23242819, 2013). "AXL is activated in tumor cells by growth arrest specific gene 6 (Gas6), a soluble serum protein, in an autocrine fashion." (PMID 23077658, 2012). "In summary, indicators of tumour and host biology such as Gas6, CD68 and Notch are helpful for improving the prediction of prognosis after NSCLC, but MMP2 and Cox2 were of no clinical value in the present study." (PMID 21794149, 2011). "The quantity of Axl mRNA in 786-O cells was very high relative to Gas6 mRNA levels and relative to Axl mRNA levels in the pair of matched normal and tumor RCC tissues." (PMID 19888345, 2009). "Some have been shown previously to be of importance for tumor growth, invasion, metastasis and/or chemotaxis, such as Gas6/AXL and CXCL1." (PMID 19558675, 2009). "This can be exemplified by the Gas6/AXL system where the addition of antibodies against the protein Gas 6 potentiated the inhibition elicited by the NPC on the N29 tumor and to a lesser extent on N32." (PMID 19558675, 2009). "The tumour group with low Gas6 levels was found to have infiltrating margins on histology, whereas the group with high Gas6 levels was found to have pushing margins." (PMID 18283315, 2008). "Tumours with low Gas6 levels were found to have high NPI scores (average=5.1, poor prognosis) and those with high Gas6 expression had low NPI scores (average=3.94, moderate 1 prognosis)." (PMID 18283315, 2008). "SWINGN (also known as LINC00565) has recently been characterized as a functionally relevant long non-coding RNA that interacts with SWI/SNF chromatin remodeling complexes and modulates a tumor-promoting transcriptional program, including activation of GAS6 and other oncogenic genes." (PMID 41467176, 2025).